TCF21 (transcription factor 21)
Diseases named in the same sentence as TCF21 in open-access papers (continued):
Sharing a sentence is not in itself a finding about the gene and the disease.
tumor (continued). "Therefore, circMEMO1 can promote the demethylation process and increase the expression of TCF21 and can be considered a crucial epigenetic modifier and an important tumour suppressor in HCC progression." (PMID 33985545, 2021). "Transcription factor 21 (TCF21) is a well-characterized tumor suppressor." (PMID 34692550, 2021). "TCF21 is also deregulated in several types of cancers and functions as a tumor suppressor." (PMID 28811522, 2017). "Therefore, in the future, more studies should be conducted to elucidate the mechanisms of TCF21 tumor suppressor function." (PMID 28515486, 2017). "All these data pointed to the conclusion that TCF21 greatly reduced tumor growth in a mouse model." (PMID 27894084, 2016). "A substantially higher tumor growth rate was observed in mice that received both shTCF21 and curcumin, compared to mice that received only curcumin, which was consistent with the positive correlation between TCF21 expression and patient survival." (PMID 27894084, 2016). "On the other hand, overexpressing TCF21 inhibits tumor growth in a H1299 mouse tumor model." (PMID 27894084, 2016). "Indeed, MTHFR, OPCML, TNFRSF25 and TCF21 show highly statistically significant differences (p < 1 × 10-6) between tumor and adjacent non-tumor tissues in our study." (PMID 18616821, 2008). "The epigenetically inactivation of TCF21 is associated with regulation of epithelial–mesenchymal transition (EMT), invasion, metastasis, cell cycle, and autophagy in different tumors, and might be an important role in tumor development." (PMID 35201460, 2021). "Therefore, TCF21 may function as an important tumour suppressor and was downregulated in HCC samples due to aberrant DNA promoter methylation." (PMID 33985545, 2021). "However, we know little about the tumor suppressor mechanism of TCF21." (PMID 28515486, 2017). "Fibroblasts aid tumor cells in undergoing EMT through cytokines like IL-6 and transcription factor 21 (TCF21)." (PMID 41276852, 2025). "When focusing on regulatory patterns, we found that CAFs displayed distinct cell type-specific TFs alongside shared TFs widely involved in carcinogenesis, including various tumor promoters or tumor suppressors, such as KLF4, NFIA, TCF21, NFKB1, and EGR1." (PMID 39872221, 2025). "TCF21 is a tumor-suppressor gene regulating the cell cycle, and the TARID-regulated mechanism allows TCF21 expression in normal cells while both TARID and TCF21 are hypermethylated, and hence downregulated, in cancer cells." (PMID 38203767, 2024). "A previous study has shown that TARID activated TCF21 expression by interacting with both the TCF21 promoter and GADD45A during tumor development." (PMID 36401313, 2022). "Previous study demonstrated that TCF21 was a master regulator of CAF status, and its overexpression diminished the ability of CAF to contract collagen gels, promote tumor growth, invasion and chemotherapy resistance." (PMID 36138435, 2022). "The downregulation of TCF21 reverts the MET process favoring migration and tumor invasion as reported in colorectal tumors, esophageal squamous cell carcinoma and urogenital cancers." (PMID 35201460, 2021). "In cultures of ACA cells obtained from pediatric tumor fragments, ACA-T7 cells, TCF21 silencing by small interfering RNA led to an increase in SF1 mRNA expression." (PMID 33729392, 2021). "We identified circMEMO1 as a crucial tumour suppressor in HCC metastasis and stemness that functions via the miR-106b-5p/TET1/5hmC/TCF21 axis and EMT process." (PMID 33985545, 2021).
tumor (continued). "Our analysis showed that HHIP was mainly located in the nucleoplasm of A‐431, U‐2 OS and U‐251 MG cells, and TCF21 and HHIP were significantly downregulated in human tumour tissues when compared to the levels in the corresponding adjacent tissues." (PMID 32525231, 2020). "TCF21 and HHIP expression levels were also significantly lower in tumour tissues than in the non‐tumour tissues of the mice." (PMID 32525231, 2020). "This list includes known tumour suppressors such as the nuclear receptor NR3C2, the helix-loop-helix transcription factor TCF21, and SMARCA2 (also known as BRM), a member of the SNF/SWI chromatin remodelling complex." (PMID 27562343, 2016). "TCF21 hypermethylation and decreased TARID expression were validated in an independent set of CCSK tumor samples." (PMID 26158413, 2015). "Of these, eight showed highly significant hypermethylation in tumor tissue (p < 0.0001): GDNF, MTHFR, OPCML, TNFRSF25, TCF21, PAX8, PTPRN2 and PITX2." (PMID 18616821, 2008). "In conclusion, AKAP12 might be a tumor suppressor in LUSC, which was mediated by TCF21 and could inhibit cell growth, metastasis, and glycolysis to restrain LUSC malignant progression." (PMID 40226362, 2025). "TCF21 binds directly in the E-box promoter sequence of steroidogenic factor 1 (SF1/NR5A1), decreasing SF-1 transcription in both the human ACC cell line (H295R) and in ACC cell culture obtained from patient tumor fragment (ACC-T36)." (PMID 33729392, 2021). "The tumor suppressor function of TCF21 has not been functionally addressed in ccRCC cells; we aimed to explore the functional potential of TCF21 expression in ccRCC cells in vitro." (PMID 29080283, 2018). "To fill this gap and explore the effect of POD-1 in cell cycle regulation in tumor cells, we investigated whether POD-1/TCF21 regulates LRH-1 and SHP in adrenocortical and hepatocarcinoma cell lines." (PMID 26421305, 2015). "Thus, it was proposed that MMP-8 is a tumor protective factor, but as far as we know, there is no report of the action of TCF21 in regulating MMP-8 expression." (PMID 35201460, 2021). "Not only have known tumor suppressor genes like Cdkn2a (p16), Itga4 (α 4-integrin), and Igfbp7 been identified as targets of aberrant methylation in cancer by RLGS, but also novel tumor suppressor genes such as TCF21, SLC5A8, ID4, BMP3B, and SOCS1 have been identified by RLGS." (PMID 18053125, 2007). "Overall, our findings demonstrated that the downregulation of TCF21 in NSCLC might result in an enhanced immunosuppressive effect of TAM, which is not conducive to tumor management." (PMID 37765264, 2023).
cancer (37 papers, 2011 to 2025). A tumor composed of atypical neoplastic, often pleomorphic cells that invade other tissues. "The anti-cancer effects of curcumin are associated with upregulation of TCF21, mediated by downregulation of DNMT1." (PMID 27894084, 2016). "Thus, the loss or reduced expression of TCF21 has been reported as a signature for malignant cancers." (PMID 27894084, 2016). "This was preceded by in-silico studies with the same conclusion that TCF-21 is a gene that is up-regulated in cancer cells." (PMID 38097858, 2024). "Transcription Factor 21 (TCF21) is a critical transcription factor involved in various types of cancers." (PMID 38714991, 2024). "TCF21 is downregulated and plays protective roles in various malignant tumors, such as hepatocellular carcinoma, ovarian cancer, and renal tumors." (PMID 38714991, 2024). "Owing to its crucial role in transcriptional regulation, TCF21 has great potential as an efficient therapeutic target for a number of cancers." (PMID 33985545, 2021). "While genes such as PTH1R, DPT, DES, TCF21 and PDE2A are downregulated in many cancers, cell cycle associated genes, centromere proteins and kinesin family proteins are upregulated in all the cancer types we studied." (PMID 34728699, 2021). "Previously performed clinical studies on the prognostic impact of TCF21 expression in ccRCC tissue revealed that TCF21 expression levels significantly correlated with Fuhrman nuclear grade and cancer‐specific survival of ccRCC patients." (PMID 29080283, 2018). "TCF21 acts as a tumor suppressor gene and a decrease in TCF21 resulted in increased undifferentiated mesenchymal cells, which in turn increased cancer cell migration." (PMID 28476165, 2017). "As expected, curcumin and TCF21 individually exerted similar inhibitory effect on these cancer cells." (PMID 27894084, 2016). "TCF21 downregulation is associated with EMT, a process that generates cancer stem cells (CSC) and promotes cancer cell migration, invasion and metastasis." (PMID 27894084, 2016). "For other genes or regions, e.g. DLX5, GRASP Region 3, IRX1, MMP2, NPY, PDX1 and TCF21, significant levels of methylation were evident in the matched normal tissue but methylation was always significantly increased in the cancer tissue." (PMID 24485021, 2014). "TCF21 was also mentioned as a promising cancer gene marker in a report that focused on the differential methylation of a short CpG-rich sequence." (PMID 22369099, 2011). "Using scRNA-seq data, we investigated the expression of genes involved in stromal-like signature (FAP, VIM, and ITGB1); cancer-associated fibroblasts (CAFs; POSTN and ACTA2); as well as COL1A1, SULF1, TCF21, and DLK1, which were previously associated with FAP-high or FAP-low CAF phenotypes in OC." (PMID 39634630, 2024). "We found that MSC, NFIA, NFIC and TCF21 were significantly effective regulons for fibroblasts in more than three cancers, indicating that they might be crucial in driving changes in cell state." (PMID 36772945, 2023). "TCF21 encodes a transcription factor involved in mesenchymal-to-epithelial transition (MET) and in the repression of epithelial-to-mesenchymal transition (EMT is therefore important in cancer cell dissemination)." (PMID 34639015, 2021). "In general, the proposition is that TCF21 is downregulated primarily by DNA hypermethylation, rather than genetic mutations, in malignant tumors." (PMID 33729392, 2021).
cancer (continued). "In addition, the TCF21 mRNA level was downregulated in a series of cancers, including HCC, compared with normal tissues, and its level in HCC samples was related to HCC patient prognosis." (PMID 33985545, 2021). "We therefore suggest that TCF21 expression moderately suppressed proliferation of this 786‐O cancer cell line and that the hypothesis that proliferation is suppressed by TCF21 warranted further investigation." (PMID 29080283, 2018). "In addition, among adult malignant tumors, the combined expression of TCF21 and BUB1B was a good predictor of OS." (PMID 29520253, 2018). "Importantly, Exo./curcumin treatment upregulated TCF21, suggesting that the TCF21 is involved in the anti-cancer effect of curcumin." (PMID 27894084, 2016). "It is well known that TCF21 is protective for multiple human cancers and it will be of great interest to determine whether expression of this gene in disease-related cells inhibits or promotes vascular disease processes." (PMID 24676100, 2014). "Importantly, TCF21 expression is epigenetically inactivated in different types of human cancers." (PMID 33729392, 2021). "In addition, it could be found that TCF21 is a predictor of overall survival (OS) in adult carcinomas." (PMID 35201460, 2021). "Additionally, decreased expression of TCF21 is a poor prognostic factor for cancer patients." (PMID 28515486, 2017). "This selection was mainly in view of the pivotal role of these genes in renal function (KCNJ1), cancer (SFRP1) and cell differentiation (TCF21)." (PMID 24194935, 2013). "TCF21, a member of the class II bHLH transcription factor superfamily, has been shown to undergo abnormal methylation and is often inactivated in human cancers, and RBP1 that seems to be involved in different types of cancers including HCC." (PMID 41231825, 2025). "TCF21 and SMARCA2 have been reported to participate in the multiple steps of the invasion of several cancers, such as proliferation, chemoresistance, and migration, suggesting the convergence of targets among the different cancers." (PMID 33968720, 2021). "In addition, the subtraction of gene expression of TCF21 and BUB1B can be a good predictor of OS in adult carcinomas, whereas the TCF21-NR5A1 can be a molecular predictor of malignancy in pediatric ACTs." (PMID 29520253, 2018). "Therefore, curcumin exerts its anti-cancer function by downregulating DNMT1, thereby upregulating TCF21." (PMID 27894084, 2016). "Similarly, our model identified genes that are frequently affected by aberrant methylation in other diseases such as cancer, including the tumor suppressors deleted in cancer 1 (DLC1) and transcription factor 21 (TCF21)." (PMID 24603652, 2014). "We conclude that TCF21 directly affects expression of CDH1, although possibly the cancer cell line we used does not have the intrinsic ability to incorporate significantly more E‐cadherin into the plasma membrane." (PMID 29080283, 2018).
cardiovascular disease (6 papers, 2017 to 2024). "Together, all these data indicated that TCF21 might confer genetic susceptibility to cardiovascular disease." (PMID 32582717, 2020). "Some of these differences were visualized by mapping the SMAD3 differential gene expression values onto the TCF21 “cardiovascular disease” transcriptional network." (PMID 30307970, 2018). "EAT, PVAT and, to a lesser extent, pericardial adipose tissue are novel types of adipose tissues that are mainly derived from tcf21 positive CPFs and play an important role in the pathogenesis of cardiovascular diseases." (PMID 29038558, 2017). "Importantly, TCF21 plays a critical role in cardiovascular diseases by regulating the differentiation of epicardium, and its absence may cause morphological epicardial defects in the early stage of cardiac development." (PMID 39519164, 2024). "TCF21, CDH19, XG, and NNAT might serve as feature genes for CAD, providing new insights for future research on the pathogenesis of cardiovascular diseases." (PMID 36345357, 2022). "In addition, the four feature genes identified (TCF21, CDH19, XG, and NNAT) might serve as feature genes for CAD, bringing new insights into the pathogenesis of cardiovascular diseases." (PMID 36345357, 2022).
infection (2 papers, 2017 to 2024). The state of being infected such as from the introduction of a foreign agent such as serum, vaccine, antigenic substance or organism. "In cultured PKR1-overexpressing tcf21+ CPFs caused by Adv-PKR1 infection, the expression of PPARγ and CEB/Pα was decreased, whereas Flk-1 and calponin expression was increased, indicating the cell-autonomous regulation of tcf21+CF cell fate by PKR1." (PMID 29038558, 2017).
kidney diseases (2 papers, 2020 to 2023). "Focusing on the influence of TCF21 on kidney diseases, we observed differences between previously published reports and the present study." (PMID 32661376, 2020). "Thus, both the increase of TCF21 expression of injured kidney segments including podocytes and its appearance in the urine may lead to urinary TCF21 elevation in various kidney diseases." (PMID 32661376, 2020).
head and neck tumors (1 paper, 2021). "The transcription factor TCF21 is involved in the differentiation of mesenchymal cells into epithelial cells, and its abnormal methylation occurs in lung and head and neck tumors." (PMID 33747902, 2021).
TCF21 also shares sentences with these, for which no sentence is quoted: kidney cancer (2 papers); adenocarcinoma (1); Arterial thrombosis (1); cervical cancer (1); chronic hepatitis B (1); clear cell sarcoma of the kidney (1); congenital mesoblastic nephroma (1); dyslipidemia (1); esophageal squamous cell carcinoma (1); glioma (1); Hydroureter (1); hyperlipidemia (1); malaria (1); male infertile (1); nephrosis (1); pancreatitis (1); pulmonary emphysema (1); Renal cyst (1); renal rhabdoid tumors (1); reproductive diseases (1); rheumatoid arthritis (1); squamous cell carcinoma (1); Stenosis (1); tuberculosis (1); urothelial cell carcinoma (1).